BRAF (B-Raf proto-oncogene, serine/threonine kinase)
Diseases named in the same sentence as BRAF in open-access papers (continued):
Sharing a sentence is not in itself a finding about the gene and the disease.
melanoma (continued). "Increased polyamine transport activity has been reported to be linked to BRAF inhibitor resistance in BRAF-mutated melanomas." (PMID 32824193, 2020). "Since anti-PD1 antibodies are widely applicable for the treatment of both BRAF wild-type and mutated advanced melanomas, several clinical trials for drugs in combination with anti-PD1 antibodies are ongoing." (PMID 32948031, 2020). "To date, the FDA has approved the combination of dabrafenib and trametinib for melanoma and lung cancer with the V600E BRAF mutation." (PMID 32984002, 2020). "There is an urgent need to develop treatments for patients with melanoma who are refractory to or ineligible for immune checkpoint blockade, including patients who lack BRAF-V600E/K mutations." (PMID 32764384, 2020). "BRAF mutation has been shown to downregulate HLA class I and tumor antigen expression on melanoma cells." (PMID 32894202, 2020). "It is well known that the BRAF mutations present in approximately 50% of melanomas trigger metabolic reprograming from oxidative phosphorylation to glycolysis." (PMID 32213878, 2020). "Nowadays, it is well known that approximately 60% of melanomas harbor a mutation in the gene encoding for the serine/threonine protein kinase BRAF, which leaded to the development of selective BRAF inhibitors such as vemurafenib and dabrafenib." (PMID 32366871, 2020). "The effect of DOX on proliferation was comparable to that of TIG, though surprisingly the BRAF-mutated melanoma cell line A375 showed resistance." (PMID 33007949, 2020). "In contrast, our BRAF-mutated melanoma cell lines displayed high levels of glycolysis and OXPHOS complex activity." (PMID 33007949, 2020). "About 50% of melanomas have activating BRAF mutations (BRAFV600E) leading to enhanced proliferation and survival." (PMID 32477956, 2020). "This cohort included patients in which NGS testing revealed positivity for targets such as HER2/neu (ERBB2) in breast cancer specimens, androgen receptor (AR) in prostate cancer, BRAF in melanoma and EGFR mutation in NSCLC." (PMID 32760731, 2020). "High expression level of MEK1/2-ERK1/2 cascade is common in melanoma, because its BRAF(V300E) mutation accounts for 50% of malignant melanoma." (PMID 33392197, 2020). "For this reason, we expanded our analysis to include rare melanoma subtypes of mucosal and acral, which often lack BRAF hotspot mutations." (PMID 32764384, 2020). "Here, we studied the effect of hypoxia on the EV and cell content of four melanoma cell lines, two carrying a BRAF V600E mutation and two carrying an NRAS mutation, using qPCR arrays (EVs), miRNA microarrays (WCLs) and mass spectrometry." (PMID 32183388, 2020). "In conclusion, no new safety and efficacy concerns were observed in this interim analysis of PMS in Japanese patients with unresectable melanoma with BRAF mutation who received dabrafenib and trametinib in the real-world clinical setting." (PMID 32699976, 2020). "Thereby, this compound potentiated the efficacy of MAPKi in BRAF-mutated melanoma cells in vitro and in vivo." (PMID 33202944, 2020). "Combination treatment with BRAF and MEK inhibitors is recommended in patients with BRAF mutated malignant melanoma." (PMID 33043759, 2020). "The activating BRAF mutation has been considered to be a main factor driving the initiation of melanoma." (PMID 32373541, 2020). "This concept was exemplified in BRAF V600E mutated melanoma models exposed to kinase inhibitors, conferring immediate clinical relevance on these findings." (PMID 32752193, 2020). "The aim of this study was to investigate the use of radiomics analysis for non-invasive identification of BRAF mutation in patients with melanoma brain metastases, based on conventional magnetic resonance imaging (MRI) data." (PMID 32313236, 2020). "For comparison, a previous study on BRAF mutation profiling in melanomas report a VAF below 20% only in 28% of samples and below 10% in 13%." (PMID 32188503, 2020).
melanoma (continued). "Cobimetinib, a MEK1 inhibitor, has been approved in combination with vemurafenib, a BRAF inhibitor, for the treatment of melanoma with BRAF V600E or V600K mutation." (PMID 33168044, 2020). "First, we introduced the MAP2K1 p.E203K mutation (c.G607A) into human A375 melanoma cells carrying a homozygous BRAF V600E mutation (c.T1799A)." (PMID 32242071, 2020). "Despite significant progress in melanoma survival, therapeutic options are still needed in case of progression under immune checkpoint inhibitors (ICI), and resistance to targeted therapies (TT) in BRAF-mutated melanomas." (PMID 32585901, 2020). "As a result, BRAF V600 mutation testing is only done in research settings and treatment for melanomas is commonly limited to surgery and cytotoxic chemotherapy (dacarbazine)." (PMID 32188503, 2020). "Taken together, these data indicate that ERBB4 mutations appear to function as tumor drivers in BRAF wild-type melanomas by cooperating with elevated RAS signaling." (PMID 33378376, 2020). "A mutation in BRAF gene is found in approximately 50% of melanoma, resulting in a constitutive activation of RAF-MEK-MAPK pathway, leading to cellular proliferation, survival and differentiation." (PMID 32674468, 2020). "Here, we report that L/L metabolism is observed in BRAF-mutated melanoma cells that enter a drug-tolerant “idling state” upon long-term MAPK inhibition (MAPKi)." (PMID 32923395, 2020). "Apart from its theragnostic implications, the prognosis value of BRAFV600 in melanoma remain controversial; several studies reported association of BRAF mutations with reduced survival, whereas others did not." (PMID 32784823, 2020). "By using a panel of melanoma cell lines harboring BRAF(V600E) mutation, the Authors showed that the BRAFi resistance leads to c-Jun and STAT3-mediated increase of PD-L1 expression." (PMID 32604720, 2020). "Knocking down AURKB inhibited cell growth and induced apoptosis in melanoma, which was associated with the BRAF/MEK/ERKs and PI3-K/AKT signaling pathways." (PMID 32863956, 2020). "•BRAF inhibitor Vemurafenib can significantly prolong the progression free survival of melanoma patients with BRAF mutation, but drug resistance limits the clinical efficacy of Vemurafenib." (PMID 32382617, 2020). "This suggests that Indonesian melanoma cases have a high BRAF V600 mutation prevalence, but at low intratumoral mutation rates." (PMID 32188503, 2020). "This factor is crucial for melanoma resistance to BRAF and MEK inhibitors, which is associated with increased levels of CD20 and IGF-1 mRNA in tumors and IGF-1 expression in tumor-associated B lymphocytes." (PMID 33171792, 2020). "In high-risk operable or in inoperable stage III and IV melanoma, the most frequently mutated genes are BRAF, NRAS, and c-KIT." (PMID 32054005, 2020). "In recent years, melanoma incidence has continued to increase worldwide, and the onset of malignant melanomas is reportedly affected by various environmental and genetic factors, such as ultraviolet exposure and carcinogenic BRAF mutations." (PMID 32825598, 2020). "Targeted therapies are indicated for the approximately 50% of melanoma patients with a BRAF V600 mutation." (PMID 32871054, 2020). "The BRAF gene is mutated in ∼7% of human cancers, including colorectal, melanoma, papillary thyroid, and non-small-cell lung cancer with variable frequency and allelic distribution." (PMID 32714388, 2020). "There is a growing body of literature indicating that mutations in common oncogenes such as BRAF correlates with poor prognosis for melanoma." (PMID 33065980, 2020). "In particular, there should be a focus towards dacarbazine, the standard single-agent chemotherapy for melanoma, immunotherapies, and targeted therapies for BRAF/MEK mutations, as the latter two have emerged within the past decade as promising treatments." (PMID 33187200, 2020). "Dabrafenib, which also targets the BRAF V600 mutation in melanoma, has demonstrated improved OS in clinical trials." (PMID 32260561, 2020).
melanoma (continued). "These mutations are frequently observed in melanoma tumors, with BRAF V600E mutants being present in up to 60% of melanoma tumors." (PMID 33256110, 2020). "BRAF activating mutations, found in 40–50% of melanomas, result in activation of the Mitogen-activated protein kinases (MAPK) pathway." (PMID 33139839, 2020). "Even more, the onset of MEK1/2 inhibitor resistance in BRAF-mutated melanoma can be forestalled by PI3K blockade." (PMID 32333246, 2020). "The high frequency of oncogenic BRAF V600E mutation reported in melanoma and melanocytic nevus suggests that activation of the RAS/RAF/MEK/ERK pathway is a critical step in the development of melanocytic diseases." (PMID 32847629, 2020). "Among the 144 patients carrying a BRAF mutated melanoma in our series, 61 DNA samples (30 cases evaluated by SS assay and 31 by pyrosequencing) were selected as adequate for further analyses." (PMID 32751423, 2020). "Although further study is needed, these results support that BRAF and MEK inhibition is an effective strategy for patients with melanoma and uncommon codon 600 BRAF mutations." (PMID 32825562, 2020). "The great variability of BRAF V600E mutational load observed in the samples analyzed, highlights the fact that tumor heterogeneity is a common feature in melanoma, where several subclones can coexist, with different abilities and behaviors." (PMID 32168325, 2020). "Patients with BRAF-mutated melanoma have shown improved PFS and OS following combination treatment with these MAPK pathway inhibitors; however, decreased clinical responses have been reported in patients following several months of treatment." (PMID 32260561, 2020). "In support of such a link, ATOX1 knockout in B-Raf proto-oncogene, serine/threonine kinase (BRAF) mutation-positive melanoma cells was found to reduce MAPK signaling." (PMID 31898157, 2020). "EGFR-directed treatment strategies were introduced in colorectal adenocarcinomas wild-type for NRAS and KRAS and BRAF inhibitor treatment finds application in BRAF V600E mutated malignant melanomas." (PMID 33227073, 2020). "For melanoma, we always profiled three different BRAF hotspot mutations in parallel (i.e., BRAF V600E, BRAF V600K, and BRAF V600R) and found two BRAF V600E and one BRAF V600K mutation in three patients who did not receive any systemic treatment at testing." (PMID 32748806, 2020). "Mutations in BRAF are seen across many cancers including, but not limited to thyroid, melanoma, colon, squamous cell and hairy cell leukemia, and CNS-related malignancies." (PMID 32411231, 2020). "BRAF mutations were reported in a large proportion of cases of malignant melanoma, papillary thyroid cancer, colon cancer, and hairy cell leukemia with poor outcomes." (PMID 32556513, 2020). "The efficacy of this modality was also demonstrated in PDX models using gain-of-functional mutated NRAS-driven malignant melanoma and BRAF(V600E)-driven colorectal cancer." (PMID 31910904, 2020). "By using a set of sequencing techniques and immunohistochemistry, this work reports the genomic and clinical features of two melanoma patients showing a rare complex mutation affecting codon V600 and K601 of the BRAF gene, leading to a V600E2; K601I change." (PMID 32754440, 2020). "In case of melanomas arising on pre-existing nevi, particular care should be taken during the enrichment process to make sure that only melanoma cells are isolated from the tissue sample, as also melanocytic nevi can carry BRAF mutations." (PMID 32695793, 2020). "There are fewer options for treating BRAF wild-type advanced melanoma than for the BRAF-mutated population." (PMID 31839677, 2020). "Further analysis of previous sequencing results showed that EZH2 mutations in human melanoma co-occur with activating mutations in BRAF (p = 0.006) and are mutually exclusive with NRAS mutations (p = 0.004)." (PMID 33024276, 2020).
melanoma (continued). "As recently reported, potential markers in melanoma are mutations (on BRAF, NRAS, KIT, GNA11/GNAQ, NF1, CDKN2AI, immunohistochemical biomarkers (such as PD-11 and PD-L1, as well as mutated BRAF and NY-ESO-1), miRNAs, and other serum molecules." (PMID 33302400, 2020). "Studies of a murine melanoma model have revealed that tumorigenesis is closely related to the inactive BRAF mutation (D594A) and oncogenic RAS." (PMID 33198372, 2020). "This dysregulation is mostly caused by the fact that the majority of melanomas harbor a mutation on the serine–threonine kinase BRAF (V600), which is part of the MAPK signaling pathway." (PMID 33014862, 2020). "Our analysis also confirmed that Melanoma-molGPA, which incorporated BRAF mutation status into its calculation, is a prognostic factor for LC." (PMID 32059731, 2020). "BRAF mutations are present in approximately 60% of melanomas, with a variability established by histologic subtype, anatomical location, sun exposure pattern, ethnicity and geographical provenience." (PMID 33419275, 2020). "In primary melanomas, mutations most often occur in either the BRAF or the RAS genes, while concomitant mutations in both were in general not observed except for in nodular melanoma." (PMID 32605090, 2020). "Mutational activation of the BRAF proto-oncogene in melanocytes reliably produces benign nevi (pigmented ‘moles’), yet the same change is the most common driver mutation in melanoma." (PMID 33047672, 2020). "It is worth noting that the significance of BRAF mutation in melanomas is still a controversial issue." (PMID 32083130, 2020). "As some studies identified BRAF mutation as a prognostic factor of melanoma patients, we performed survival analysis using the Kaplan–Meier method." (PMID 32143442, 2020). "Over 50% of melanomas harbor activating mutation in the BRAF gene, which sustains proliferation and survival of melanoma cells by activating the MAPK pathway." (PMID 32604720, 2020). "NCT01673854 is investigating the safety of vemurafenib, administered at 960 mg for 6 weeks along with ipilimumab in a sequential manner, to BRAF V600-mutated melanoma patients." (PMID 32260561, 2020). "More recently, new oncogene-targeting chemotherapeutic agents have shown promising effects especially in tumors mutated on KRAS, NRAS and BRAF including melanoma." (PMID 31906480, 2020). "In preclinical studies binimetinib inhibited the growth of NRAS and BRAF mutated melanoma tumor cells." (PMID 32850962, 2020). "Broadly speaking, BRAF-mutated melanomas are characterized by more aggressive clinical features than wild-type ones." (PMID 33260892, 2020). "Trametinib, a specific MEK inhibitor, is mainly used for the treatment of adult patients with unresectable melanoma or metastatic melanoma who carry either the BRAF V600E or the V600K mutations." (PMID 32306562, 2020). "The mutated BRAF melanomas had a 33% response while the wild-type BRAF tumors only had a 10% response." (PMID 33256089, 2020). "We then demonstrated that Gal-1 is a novel driver of resistance to BRAF inhibitors in melanoma and that its activity is linked to the concomitant upregulation of the NRP1 receptor observed in drug-resistant cells." (PMID 32784465, 2020). "Activating BRAF mutations (e.g. BRAFV600E) are the most common oncogenic mutations in melanoma, seen in about 66% of cases." (PMID 33047672, 2020). "Transcriptome-wide profiling of patient-derived melanoma samples has led to the identification of specific signatures associated with major oncogene subtypes (e.g., BRAF-mutant, NRAS-mutant, NF1-mutant, and triple wild-type) and prognoses." (PMID 33024276, 2020). "The MAF of a BRAF G469A mutation based on ctDNA using our custom panel was found to be <0.2% in two stage IV melanoma patients." (PMID 32785074, 2020).
melanoma (continued). "For example, the outcome of a phase II randomized clinical trial suggests that the BRAF inhibitor vemurafenib prolongs the survival of patients with advanced melanoma carrying the BRAFV600E mutation." (PMID 32934956, 2020). "Uncontrolled production of reactive oxygen species (ROS) by TME fibroblasts is also associated with resistance to BRAF-targeted agents in melanoma." (PMID 33036192, 2020). "Activation of the PI3K-AKT pathway, through the loss of PTEN and BIM down-modulation, prevents melanoma cell apoptosis and stimulates cell growth, thus leading to BRAF inhibitor resistance." (PMID 33233603, 2020). "In light of current evidence, immune checkpoint inhibitors are considered a standard treatment for patients with CM, and BRAF/MEK inhibitors are recommended in patients with melanoma and BRAF V600E/K mutations." (PMID 32825562, 2020). "BRAF gene mutations are considered as driver mutations due to their presence in nevus, correlated to the development of melanoma and PMs and metastasic outgrowths." (PMID 31274706, 2020). "In the phase III COMBI-AD trial, 870 patients diagnosed with IIIA (with lymph node metastasis >1 mm), IIIB and IIIC BRAF-mutated melanoma were treated with dabrafenib plus trametinib or placebo for 1 year." (PMID 32760738, 2020). "A higher proportion of patients in the IL-2 monotherapy cohort had melanomas with a BRAF V600E mutation compared with those assigned to SBRT + IL-2 (55% vs 29%, p=0.1)." (PMID 32467299, 2020). "The prevalence of BRAF V600 mutations in melanoma patients from Indonesia has also been shown to be relatively low." (PMID 32188503, 2020). "Approximately one-half of melanoma harbors a BRAF mutation, mostly at codon 600: this molecular activation occurs early during melanoma evolution, driving both cancer growth and dissemination." (PMID 32054102, 2020). "To date, melanoma with non-V600 BRAF mutations has been mostly excluded from enrollment in clinical studies investigating the efficacy of BRAF and MEK inhibitors." (PMID 33233603, 2020). "To systematically investigate BRAFi resistance mechanism in melanoma, we conduct a series of experiments in BRAF (V600E)-mutated cell lines that had obtained resistance to the BRAFi PLX4032 following chronic exposure." (PMID 32413516, 2020). "This is expected, as vemurafenib is a selective inhibitor of V600E-mutant BRAF, and this mutation is present in approximately 60% of melanomas." (PMID 33370253, 2020). "Here, we identified pyridinyl imidazole compounds SB202190, SB203580, and SB590885 as dual inhibitors of critical proliferative pathways in human melanoma cells bearing the V600E activating mutation of BRAF kinase." (PMID 32531927, 2020). "Wolf and colleagues reported the results of one of the first prospective experiences on the association of SRS with BRAF inhibitors in the treatment of melanoma patients who developed brain metastases." (PMID 32366258, 2020). "We observed the expected frequency of described BRAF mutated melanomas (38%) in the subset of samples where the technique was performed." (PMID 36046072, 2020). "Our results confirmed the previously suggested combinatorial inhibition of the MAPK/ERK pathway as an effective and safe treatment for malignant melanoma with BRAF V600E mutation." (PMID 33370253, 2020). "The largest was cohort A, including 76 patients with BRAF V600E mutated melanoma, asymptomatic brain metastasis, ECOG performance status (PS) 0-1 with no previous local brain treatments." (PMID 32575838, 2020). "Testing for BRAF mutations is now globally recommended in order to choose the most appropriate therapy for patients with stage III or IV melanoma." (PMID 33003483, 2020).